ULBP1 (UL16 binding protein 1)
Description:
Binds and activates the KLRK1/NKG2D receptor, mediating natural killer cell cytotoxicity.
Synonyms: N2DL-1; NKG2DL1; RAET1I
Tractability: Antibody: UniProt places it where antibodies can reach, with high confidence; its Gene Ontology location is reachable by antibodies, with high confidence; UniProt predicts a signal peptide or a membrane-spanning region; the Human Protein Atlas places it where antibodies can reach.
Gene: Protein-coding gene on chromosome 6 (149,963,943 to 149,973,715, forward strand). Ensembl gene ENSG00000111981.
Subcellular location: Cell membrane; Endoplasmic reticulum
Subcellular location (Human Protein Atlas): Cytosol; Plasma membrane
Pathways (Reactome):
Immune System: Immunoregulatory interactions between a Lymphoid and a non-Lymphoid cell
Gene Ontology:
Molecular function: natural killer cell lectin-like receptor binding; protein binding; receptor ligand activity
Biological process: natural killer cell activation; natural killer cell mediated cytotoxicity; antigen processing and presentation of endogenous peptide antigen via MHC class I via ER pathway, TAP-independent; antigen processing and presentation of endogenous peptide antigen via MHC class Ib; positive regulation of T cell mediated cytotoxicity; signal transduction
Cellular component: endoplasmic reticulum; plasma membrane; external side of plasma membrane
Genetic constraint (gnomAD): Loss-of-function variants: 28 observed, 26.87 expected, observed/expected ratio (o/e) 1.04, 90% interval 0.77 to 1.43. The upper end of that interval is the gene's LOEUF score, 1.43, which puts it in group 5 of 6, group 1 being the genes least tolerant of losing a copy. Missense variants: 348 observed, 300.17 expected, observed/expected ratio (o/e) 1.16, 90% interval 1.06 to 1.27. Synonymous variants: 129 observed, 109.52 expected, observed/expected ratio (o/e) 1.18, 90% interval 1.02 to 1.36.
Homologues: Orthologues: chimpanzee ULBP1 (98% identical), pig ULBP1 (44% identical), mouse Ulbp1 (27% identical), zebrafish mhc1laa (15% identical), tropical clawed frog mhc1-uea (14% identical), zebrafish mhc1lja (14% identical), zebrafish mhc1lda (14% identical), zebrafish si:dkey-52p2.5 (14% identical), zebrafish mhc1lfa (13% identical), zebrafish mhc1lla (13% identical), zebrafish mhc1lca (13% identical), zebrafish mhc1lga (12% identical), and 1 more. Paralogues in human: RAET1L (61% identical), RAET1G (60% identical), ULBP2 (60% identical), ULBP3 (54% identical), RAET1E (38% identical), HLA-E (26% identical), HLA-C (25% identical), HLA-G (25% identical), HLA-A (25% identical), HLA-B (25% identical), HLA-F (25% identical), MR1 (24% identical), and 10 more.
Diseases named in the same sentence as ULBP1 in open-access papers:
ULBP1 is named in the same sentence as 84 diseases in open-access papers, as found by Europe PMC text mining. Sharing a sentence is not in itself a finding about the gene and the disease. The quoted sentences say what the papers report.
hepatocellular carcinoma (20 papers, 2016 to 2025). A malignant tumor that arises from hepatocytes. "The NKG2D ligand ULBP1 is upregulated by circARSP91 at mRNA and protein levels, thereby enhancing the responsiveness of hepatocellular carcinoma (HCC) cells to NK cells." (PMID 35464462, 2022). "Subsequent mechanistic research revealed that upregulating UL16 binding protein 1 (ULBP1) expression in hepatocellular carcinoma cells led to the enhanced innate immune surveillance, by strengthening cytotoxic NK cells." (PMID 34303380, 2021). "Subsequent mechanistic research revealed that upregulating UL16 binding protein 1 (ULBP1) expression in hepatocellular carcinoma cells led to enhanced innate immune surveillance by strengthening the cytotoxicity of NK cells." (PMID 32122338, 2020). "Moreover, ULBP1 has been shown to promote immune escape via PDCD1LG1 in hepatocellular carcinoma (HCC)." (PMID 40433389, 2025). "CircARSP91 could upregulate UL16 binding protein 1 (ULBP1), thus enhancing the cytotoxicity of NK cells toward hepatocellular carcinoma." (PMID 37762497, 2023). "Increased serum ULBP1 predicted reduced overall survival of hepatocellular carcinoma patients." (PMID 35236310, 2022). "For example, LINC00638 promotes immune escape in hepatocellular carcinoma by sponging microRNA-4732-3p and targeting UL16-binding protein 1 (ULBP1), and the lncRNA Down syndrome critical region 8 (DSCR8) interacts with microRNA-137 to facilitate gastric cancer progression." (PMID 35587748, 2022). "In hepatocellular carcinoma (HCC) cells, overexpression of circARSP91 can up-regulate the expression of ULBP1, thereby enhancing the cytotoxicity of NK cells to HCC cells." (PMID 40296917, 2025). "Certain cancerous cells, such as human hepatocellular carcinoma (HCC) cells, contain ULBP1 as a cell surface protein." (PMID 39866909, 2024). "For example, in hepatocellular carcinoma (HCC), circARSP91 upregulated the expression of UL16 binding protein 1 (ULBP1) to enhance the cytotoxicity of NK cells." (PMID 36672208, 2023). "Therefore, we next examined whether HCV infection would enhance the cell surface expression of ULBP1 through the DNA damage response in RSc cells derived from the human hepatoma cell line HuH‐7." (PMID 29511613, 2018). "EZH2 recruited DNMT3A to the promoter of ULBP1, increasing DNA methylation and thus down-regulating the expression of NKG2D ligands to resist NK-cell-mediated cytotoxicity in hepatoma cells." (PMID 37268997, 2023). "In the present study, we demonstrated that hepatitis C virus (HCV) induced the cell surface expression of ULBP1 in human immortalized hepatocyte PH5CH8 cells and human hepatoma HuH‐7 cell‐derived RSc cells." (PMID 29511613, 2018). "UL-16 binding protein 1 (ULBP1) is a ligand of the activatory receptor Natural Killer cell Group 2 receptor D (NKG2D) and is found as a cell-surface protein on some malignant cells including on human hepatocellular carcinomas." (PMID 32656081, 2020). "For instance, in hepatocellular carcinoma (HCC) cells, circARSP91 was reported to enhance the cytotoxicity of NK cells by upregulating the expression of UL16 binding protein 1 (ULBP1) at the mRNA and protein levels." (PMID 31973726, 2020). "The research revealed that ULBP1, one of the NKG2D ligands, was not expressed in poorly differentiated human hepatoma tissues and cell lines, but was abundantly expressed in hyperplastic abnormal nodules and well to moderately differentiated HCC cells." (PMID 33614486, 2020).
glioma (11 papers, 2015 to 2023). A benign or malignant brain and spinal cord tumor that arises from glial cells (astrocytes, oligodendrocytes, ependymal cells). "As a result, the level of promoter methylation for Micb, Ulbp1 and Ulbp3 is higher in gliomas with mutated IDH than with wild type IDH, and the two primary transcriptionally silenced NKG2D ligands ULBP1 and ULBP3 were responsive to DNMTi." (PMID 34681626, 2021). "The expression of ICOS, TNFSF14, and ULBP1 was assessed by immunohistochemistry in patients with glioma, confirming that TNFSF14 was associated with the clinical outcome of patients with glioma." (PMID 31451090, 2019). "It was found to restore ULBP1 and ULBP3 expression in IDH mutant glioma cells." (PMID 37274252, 2023). "Furthermore, decitabine-mediated hypomethylation restores ULBP1 and ULBP3 expression in IDH-mut glioma cells, suggesting a potential method to sensitize IDH-mut gliomas to NK cell-mediated immune surveillance in the clinic." (PMID 35267433, 2022). "Genes, such as OAS2, ULBP1, HERPUD1, and CASP4, are diagnosed with the growth of various cancers, such as oral cancer, cervical cancer, and gliomas, but these genes may identify with the development of BRCA." (PMID 31311202, 2019). "First, we monitored by flow cytometry the cell surface expression of the NKG2D ligand MICA, MICB, ULBP1, ULBP2, ULBP3, ULBP4 and MHC class I on untreated and SR141716-treated U251 glioma cells at 24 h to exclude that the possibility of observed effects are linked to the stress of dying cells." (PMID 26008966, 2015).
lung carcinoma (10 papers, 2012 to 2024). "ULBP-1 mRNA and protein expression was induced in a dose- and time-dependent manner in lung cancer cells, thereby increasing their susceptibility to NK cell cytotoxicity." (PMID 34205719, 2021). "Next, we adopted flow cytometry to assess cell surface expression of NKG2DLs, MICA/B and ULBP1 on the lung cancer cell lines including A549, H1975, and PC9." (PMID 38263004, 2024). "In our short-term co-culture system, A549 and H1975 lung cancer cells down-regulated surface expression of NKG2D ligands ULBP1, ULBP2 and MICA following co-culture with NK cells." (PMID 23937717, 2013). "AXL could affect cytotoxic immune response against tumors by reducing the expression of intercellular adhesion molecule 1 (ICAM1) and UL16 binding protein 1 (ULBP1) in mesenchymal human lung cancer cells." (PMID 37328828, 2023). "To investigate whether gefitinib could up-regulate surface ligands for NK cell activating receptors, we co-cultured two human lung cancer cell lines with NK cells and evaluated the expression of ULBP1, ULBP2 and MICA by flowcytometry." (PMID 23937717, 2013). "It has been recently demonstrated that the EGFR inhibitors gefitinib and erlotinib enhance the susceptibility to NK cell mediated lysis of A549, NCI-H23 and SW-900 lung cancer cell lines by the induction of ULBP1 (a ligand of the NK cell activation receptor NKG2D)." (PMID 23234355, 2012). "Treating NCI-H23 and A549 lung cancer cells with FK228 led to an increase in the transcription of the five NKG2D ligands: MICA, MICB, ULBP1, ULBP2, and ULBP3." (PMID 34203519, 2021). "The transcription of NKG2D ligands, namely, MHC class I polypeptide-related chain proteins A (MICA), MICB, UL16 binding protein 1 (ULBP1), ULBP2, and ULBP3, was analyzed after treating lung cancer cells with five types of HDAC inhibitor for 18 h." (PMID 34203519, 2021). "Sublethal concentrations of celecoxib increased the expression levels of UL16-binding protein 1 (ULBP-1), a natural-killer group 2 member D (NKG2D) ligand, in lung cancer A549 and H460 cell lines." (PMID 34205719, 2021). "The lung cancer cell line A549 highly expressed MICA, MICB, ULBP1, and ULBP2/5/6." (PMID 35965586, 2022). "mRNA levels of H60, Raet-1 and Ulbp1 were upregulated in cells treated with gemcitabine, indicating that chemotherapeutic stimulation induced upregulation of expression of NKG2D ligands in the lung cancer cells of mice." (PMID 32161598, 2020).
glioblastoma (8 papers, 2018 to 2024). The most malignant astrocytic tumor (WHO grade IV). "Tumor-associated myeloid cells and circulating monocytes in glioblastoma patients were found to upregulate the human NKG2D ligands ULBP1 and MICB." (PMID 29757143, 2018). "MICB and ULBP1 were also shown to be upregulated on healthy monocytes from glioblastoma patients in response to tumor-derived lactate dehydrogenase." (PMID 29483917, 2018). "Three representative glioblastoma cell lines (U251, U87, A172) were selected for assessing cell surface expression of NKG2DL (MICA/B, ULBP1, ULBP2/5/6, ULBP3, and ULBP4) by flow cytometry." (PMID 39877353, 2024). "Next, the co-expression of the glioblastoma stem cell marker NESTIN and NKG2DLs (MICA, MICB, ULBP1, ULBP2, ULBP3) in these suspended cell spheres was assessed by flow cytometry." (PMID 31288857, 2019). "Cell surface expression of the main ligands for the NKG2D receptor (MICA, MICB, ULBP1, ULBP2, and ULBP3) on the glioblastoma cell lines, U-251MG, T98G, and U-87MG, was assessed by flow cytometry." (PMID 31288857, 2019). "In glioblastoma multiforme (GBM) patients, MICA and ULBP1 were detected on microglia, tumor-infiltrating myeloid cells, and circulating monocytes." (PMID 29740438, 2018).
acute myeloid leukemia (7 papers, 2017 to 2022). Acute myeloid leukemia (AML) is a group of neoplasms arising from precursor cells committed to the myeloid cell-line differentiation. "In particular, HDACi upregulated NKG2D-L, such as MICA/B and ULBP1, on multiple tumor cell lines, both from hematological and solid tumors and on patient-derived acute myeloid leukemia (AML) cells, leading to increased sensitivity to NK cell-mediated cytotoxicity." (PMID 33572396, 2021). "In addition, elevated DNA-“hyper”-methylations for NKG2DLs could be detected in some malignant cells, mainly in acute myeloid leukemia (AML) cells, resulted in a clearance of NKG2DL surface cell expression, also detected for MICA, ULBP1/2 in AML patients." (PMID 28943878, 2017).
breast carcinoma (6 papers, 2016 to 2024). "Recognition of NKG2DLs such as MICA/B and ULBP1-3 by the activating immunoreceptor NKG2D, expressed by NK and cytotoxic T cells, stimulates anti-tumor immunity in breast cancer." (PMID 38612935, 2024). "The breast cancer cell line MB543 did not express ULBP1, but ULBP3 was partially expressed." (PMID 35965586, 2022).
colon adenocarcinoma (6 papers, 2022 to 2025). "A combination survival analysis revealed that patients with a high co-expression of ULBP1, AARS1, and DDIT3 exhibited a 2.2-fold increased risk of death from colon adenocarcinoma (COAD) compared to patients with a low expression of all three genes." (PMID 41008630, 2025). "A report showed that RAET1L together with ULBP1, ULBP2, ULBP3 had the high diagnostic values in colon adenocarcinoma (COAD)." (PMID 36294477, 2022). "On the other hand, a recent bioinformatic analysis of ULBP1 expression in colon adenocarcinoma patients revealed ULBP1 as a negative indicator of overall patient survival." (PMID 35565467, 2022).
leukemia (6 papers, 2017 to 2022). A malignant (clonal) hematologic disorder, involving hematopoietic stem cells and characterized by the presence of primitive or atypical myeloid or lymphoid cells in the bone marrow and the blood. "For example, ULBP1 expression positively correlates with leukaemia sensitivity to NKG2D-mediated lysis by γδ T cells, and loss of ULBP1 conferred resistance to lysis, whereas MICA downregulation did not." (PMID 33352921, 2020). "Consistent with this, the downregulation of ULBP1 impaired, whereas its overexpression enhanced, Vγ9Vδ2 T cell-mediated killing of leukemia/lymphoma cells." (PMID 29740448, 2018). "Moreover, when we looked for NKG2D ligands whose expression could account for leukemia cell recognition, we found ULBP1 to be the strongest candidate." (PMID 29740448, 2018). "Thus, the authors propose that γδ T cytotoxic function is achieved through a two-step process (a TCR stimulation presumably by endogenous phophoantigens and a tumor cell recognition by NKG2D) and that ULBP1 could be used as a leukemia/lymphoma biomarker in clinical trials." (PMID 28713381, 2017). "Moreover, c-Myc is often dysregulated and overexpressed in many different tumor types, including leukemia, and it drives the expression of NKG2DL in a mouse leukemia model and the expression of ULBP1/2/3 in human AML." (PMID 33918810, 2021).
multiple myeloma (6 papers, 2019 to 2024). "Myeloma cells with NLRC5 mutations and overexpression of selected genes including TNFRSF10D, NCR3LG1, ULBP1, PVR, and PCGF5 were sensitive to NK cells." (PMID 38410372, 2024). "Myeloma cells with TRAF3 and WHSC1 mutations and overexpression of TNFRSF10D, NCR3LG1, ULBP1, PVR, and PCGF5 were tolerance to NK cells." (PMID 38410372, 2024). "We analyzed the morphology of the patient primary myeloma cells for expression levels of MHC I, MICA, MICB, ULBP1, ULBP2/5/6, HLA-E, CD38 (n = 12), CD112, CD155, ICAM-1 and PD-L1 (n =5) using flow cytometry." (PMID 35413499, 2022). "Moreover, on multiple myeloma cell lines, we did not see a change in the expression of stress-induced activating ligands MICA/B and ULBP1/2." (PMID 34203549, 2021).
ovarian carcinoma (6 papers, 2017 to 2025). A malignant neoplasm originating from the surface ovarian epithelium. "Various NKG2DLs, such as MICA/B and ULBP-1, -2, -3, and -4, are expressed across established ovarian cancer cell lines and primary ovarian cancer samples." (PMID 40612946, 2025). "NKG2D CAR-T cells recognize stress ligands (MICA/B, ULBP1–6) expressed on over 80% of diverse solid tumors, including pancreatic and ovarian cancers, thereby broadening therapeutic applicability." (PMID 41007874, 2025). "We found that pharmacological inhibition of DOT1L upregulates the expression of the NKG2D ligand ULBP1 in a subset of ovarian cancer cells, leading to NK cell-mediated killing of the ovarian cancer cells." (PMID 34253709, 2021). "ULBP1 was the only NKG2D ligand that was significantly upregulated at the mRNA level in multiple ovarian cancer cell lines." (PMID 34253709, 2021). "DOT1L inhibition also resulted in the upregulation of the NKG2D ligand ULBP1 and subsequent increase in natural killer (NK) cell-mediated ovarian cancer eradication." (PMID 34253709, 2021). "Pharmacological inhibition of DOT1L additionally upregulates the expression of natural killer group 2 D (NKG2D) ligands, in particular ULBP1, which correlates with increased natural killer (NK) cell-mediated eradication of ovarian cancer cells." (PMID 34253709, 2021). "Analysis of patient-derived samples of ovarian cancer showed that the intensity and quantity of ULBP1 expression were lower in samples with high DOT1L expression than in samples with low DOT1L expression." (PMID 34253709, 2021). "Next, we measured the ULBP1 protein expression in all of the ovarian cancer cell lines." (PMID 34253709, 2021). "Finally, we find that DOT1L can suppress NK cell-mediated anti-ovarian cancer immunity, in part by repressing NK cell-activating ligands, such as ULBP1." (PMID 34253709, 2021). "We next asked whether the level of ULBP1 expression affected NK cell-mediated killing of ovarian cancer cells." (PMID 34253709, 2021). "Together, our results indicated that in a subset of ovarian cancer cell lines, DOT1L represses the expression of the activating NK cell ligand ULBP1, resulting in suppression of NK cell antitumor function." (PMID 34253709, 2021). "To assess the cytotoxic activity of CD8+ CIK cells on ovarian cancer cells, we screened a panel of ovarian cancer cell lines for the expression of NKG2D ligands including MICA, MICB and ULBP1-4 by qPCR." (PMID 28426690, 2017). "In our study, we showed in ovarian cancer cells that methyl gallate significantly enhanced the expression of stress ligands for DNAM-1 and NKG2D NK cell receptors, i.e. CD112, CD155, MIC-A/B, ULBP-1/2/3, TRAIL-1 (DR4) and TRAIL-2 (DR5)." (PMID 36899361, 2023).